IGF1 (insulin like growth factor 1)
Diseases named in the same sentence as IGF1 in open-access papers (continued):
Sharing a sentence is not in itself a finding about the gene and the disease.
tumor (continued). "The decreasing of free IGF‐1 levels led by dysfunction of PAPPA2 protein could result in an imbalanced growth hormone (GH)/IGF‐1 signalling pathway, which was related to DNA damage repair (DDR) pathway, immune system maintenance and anti‐tumour immune activation." (PMID 35811392, 2022). "Interestingly, patients with IGF-1 and tumour control that had impairment in QoL and symptoms according to paPASQ did not statistically differences in the time since diagnosis in comparison with patients with IGF-1 and tumour control that showed stable QoL and mild symptomatology (data not shown)." (PMID 34668173, 2022). "Other studies revealed that IGF-1 that is bound to IGF-1R may stimulate mitosis and cell migration, prevent apoptosis (via the activation of MAPK and PI3K signalling pathways) as well as enhance tumour angiogenesis via raising vascular endothelial growth factor levels." (PMID 35328822, 2022). "Therefore, drugs targeting EGF, IGF-1, and HGF may critically disrupt not only tumorigenesis and progression of HCC but also angiogenesis, and counteract the metastasizing potential of the tumor." (PMID 34572344, 2021). "Knockdown of IGF1 and IGFBP3 expression level via applying a CRISPR/Cas9 genome editing system could promote apoptosis in OS cells which in turn leading to downregulating the expression level of ROS and Nrf-2, and thereby enhancing the sensitivity of Graphene Oxide in tumor cells." (PMID 33768092, 2021). "The difference in Igf1-expressing myeloid cells in G-Smo and M-Smo tumors demonstrates an effect of tumor genotype on the TME that may feedback on tumor phenotype by altering tumor mTORC1 activation, and thus contribute to differences in tumor growth and recurrence." (PMID 34021242, 2021). "A possible explanation might be related to the fact that miR-186-3p targets and binds to IGF1 and inhibits the activation of specific receptor tyrosine kinases (RTKs), thereby blocking the PI3K/AKT pathway, leading to increased apoptosis and decreased tumor formation, as shown in the present study." (PMID 34551673, 2021). "In particular, Plasmodium infection can significantly decrease MMP-9 expression by regulating IGF-1, which might signal intracellularly through the PI3 and MAPK pathways after binding to IGF-1R on the cell surface and thereby increase the expression of MMPs in tumor-bearing mice." (PMID 32972437, 2020). "However, additional studies are necessary to confirm this hypothesis including the assessment of tumor IGF-1, which was not performed in the current study." (PMID 33346251, 2020). "Pegvisomant (a GH receptor antagonist) has been used in pediatrics to obtain IGF-1 normalization and symptom improvement in patients without a response to surgical treatment, radiotherapy, and SSAs, although the possibility of an increase in tumor size with this medication should be considered." (PMID 31365626, 2019). "To further investigate whether IGF-1 facilitate tumor growth in our study, we sorted CD45+ CD11b+ Gr-1+ CD215+ and CD45+ CD11b+ Gr-1+ CD215− cells from the spleen of tumor-bearing mice and cultured them with A549-GFP-luciferase cells with IL-15 or IL-15 plus anti-IGF-1 antibody." (PMID 29255466, 2017). "Against our expectation, administration of IGF1 was unable to further increase the tumor growth and metastasis in the control WT mice, suggesting that an excess of IGF1 supply over demand to the control mice could not accelerate the tumor progression." (PMID 26923183, 2016). "Also under serum depletion with addition of exogenous IGF-1 IRS-1 showed decreased phosphorylation in cells treated with compounds 1 and 2 albeit of less magnitude than when cells were cultured in serum, which was the condition where we found these compounds to have specific anti-tumor activity." (PMID 27384680, 2016).
tumor (continued). "Studies have shown that CR can enhance DNA repair in normal cells; however, this may not be the case in tumor cells, and the differential response of tumor cells and normal cells to genotoxic stress may be mediated by reduced Insulin-like growth factor 1 (IGF1) and glucose in the tumor cells." (PMID 27899882, 2016). "However, an excess of IGF1 supply over demand to the control mice could not further accelerate the tumor growth and metastasis." (PMID 26923183, 2016). "Our findings confirmed that IGF1 administration could enhance the tumor growth of EphA4‐deleted mice up to a level similar to that observed in control WT mice, but could not enhance the metastatic tumor foci of EphA4‐deleted mice up to the WT level." (PMID 26923183, 2016). "Thus, metformin may have a direct effect on tumor cells independent of its effects on circulating insulin and IGF-1." (PMID 24133632, 2013). "Over the 5-year period, the etiology of AGHD was also correlated with the mean IGF-1 SDS, which was significantly lower in patients with tumor-related compared to non-tumor-related etiology." (PMID 40076636, 2025). "Tumor cells were implanted alone or co-injected with CAFs, CAF-oeIGF1, or CAF-sgIGF1 cells, with or without IGF1-neutralizing antibody." (PMID 41275311, 2025). "Strong immunoreactivity of ESR1, APOA1, IGF1, and PON1 was observed in normal tissues, whereas weak or no staining was observed in tumor tissues." (PMID 40317014, 2025). "Neither age, sex, GH, IGF-1 (nmol/L) and IGF-1/ULN levels, tumor size (macroadenoma vs. microadenoma) and first treatment modality (surgery vs. 1st generation SSAs) predicted control at long-term follow-up." (PMID 37665404, 2023). "Three months after surgery, he presented normalisation of IGF1 levels, GH nadir during OGTT was < 1 ng/mL and no residual tumour was found on the MRI." (PMID 37149543, 2023). "In turn, EGFR, IGF1 and MAPK1 mRNA expression levels were significantly decreased, while RHOA mRNA expression was not significantly downregulated in tumor tissues." (PMID 36882618, 2023). "Marked upregulation of IGF1 was evident in tumor tissues from TMZ-resistant patients with GBM, with a corresponding negative correlation between IGF1 and miR-302a-3p in this cohort of patient samples." (PMID 36479381, 2022). "Neither GH, IGF-1 ULN, tumor size, tumor invasion, nor percentage of comorbidities at diagnosis showed statistical differences when compared to those cases diagnosed between 65 and 75 years of age." (PMID 36187107, 2022). "The decrease in serum IGF-1 levels during combined therapy was not correlated with basal GH, IGF-1, and PRL levels, the tumor size before cabergoline add-on therapy." (PMID 35612842, 2022). "Although the decrease in IGF-1 levels was not correlated with a reduction in PRL level and tumor size, in the controlled group, the tumor size was found to be larger than the other group." (PMID 35612842, 2022). "Using the 4‐tiered scale, the patients with no biochemical response (<20% reduction of IGF1) showed significantly lower H‐score of SSTR2A (P = .02, Kruskal‐Wallis) and larger tumour diameter (P = .025, one‐way ANOVA)." (PMID 33491286, 2021). "On multivariate analysis, IGF-1 levels were not a significant predictor of remission when EOR was taken into account, though preoperative tumor size did not have a significant impact (p=0.575)." (PMID 34867787, 2021). "B16-F10 cells did not express detectable levels of Gh or Igf-1 RNA, indicating perhaps a greater dependence on either circulating or paracrine GH or IGF-1 from the tumor microenvironment, rather than autocrine production." (PMID 33291663, 2020). "Other important molecules involved in the IGF-1 signalling pathway, such as IRS-1, IGF-1 receptor, pAKT and AKT did not change significantly in relation to the size of the tumour." (PMID 30410539, 2018). "No IGF-1 or IGF-2 expression was found in the cell lines (data not shown), confirming the paracrine activation of the pathway in this tumor." (PMID 25906745, 2015).
tumor (continued). "Of note, in our previous clinical trial, we locally applied IGF-1 in the middle ear of 25 patients with refractory SSHL; in the 5-year follow-up, no tumor formation was identified in those patients." (PMID 25406953, 2014). "In the last group an increase of GH-IGF1 axis (evaluated as circulating IGF1 and IGFBP3) was observed without any change in tumour-free survival rates and median tumour-free survival time." (PMID 25225571, 2014). "In univariate analyses, lymph node positivity, surgical margin positivity, non-localized tumor, age at prostatectomy, and biomarkers CCND1, HMMR, IGF1, MKI67, SIAH2, and SMAD4 in malignant epithelium were significantly associated with time to BF." (PMID 24708576, 2014). "In this study, expression levels of IGF-1, IGF-2, and their receptors were determined in paired samples of tumor and adjacent non-neoplastic liver from patients who underwent liver resection for HCC." (PMID 25052889, 2014). "In the light of this knowledge, it was perhaps not an unexpected finding that the mere presence of IGF-1 in serum, or the level of IGF-1R on the surface of tumor cells, has not been found to be a useful biomarker for tumor incidence or progression." (PMID 22348393, 2012). "Co-treatment of MCF-7 cells with IGF-1 and UO1261 resulted in miRNA expression levels that were no longer different than that of vehicle treated cells for all five tumor suppressor miRNAs." (PMID 23226206, 2012). "HRG stimulation promoted physical and functional erbB2/erbB3 interactions and tumor cell growth, whereas no response to EGF or IGF-1 was observed." (PMID 16168116, 2005). "Additionally, IGF-1 levels did not significantly correlate with liver volume, tumour volume, age, BMI, INR, ALT, or AFP, suggesting that IGF-1 does not directly reflect these HCC characteristics or patient status." (PMID 39624154, 2025). "Furthermore elevated levels of growth hormones (GH) and insulin-like growth factor 1 (IGF-1), regardless of the tumor size, can disrupt the normal pulsatility of gonadotropin secretion." (PMID 39337013, 2024). "According to this, the targeting of IGF-1 or IGF-1R will not stop the action of PEc, which apart from inducing cellular proliferation and EMT leading to metastasis and invasion also induces the recruitment of mesenchymal stem cells prior to tumor repair." (PMID 39273251, 2024). "However, IGF1-mediated activation of IGF1R is blocked by SSTNIGF1R in the tumor cells, indicating that activation of IGF1R with or without IGF1 in the tumor cells is highly dependent on its linkage to Sdc1." (PMID 36968227, 2023). "There were no significant changes in IGF-1 and TNF-α related to tumor growth." (PMID 36235844, 2022). "Although there are many biomarkers closely related to GBM, including insulin-like growth factor 1 (IGF-1), vascular endothelial growth factor (VEGF), isocitrate dehydrogenase 1 (IDH1), and epidermal growth factor receptor (EGFR), no effective tumor markers have been discovered." (PMID 35413821, 2022). "The MSCs in the hypoxic tumour microenvironment produced leptin, which is capable of inducing erlotinib resistance in lung adenocarcinoma cells through the activation of IGF-R1 signalling in the absence of IGF-1 in hypoxia." (PMID 35954425, 2022). "Moreover, tumor cells did not seem to have enough enzymes to act on pro-IGF-2; thus, the excess pro-IGF-2 competes with IGF-1 and IGF-2 in binding to IGFBP to form a 40–50–kDa binary complex." (PMID 36034453, 2022). "However, four additional GS that are not directly associated with proliferation but rather represent growth factor signalling pathways were significantly higher in non-responder tumours: ERBB2-GS, IGF1-GS, STAT1-GS, GDNF-GS." (PMID 31892336, 2019). "In contrast, IGF-1 expression was weak or absent in NPC and NPE cell lines, with the exception of the EBV-infected C666 cell line, and was found to be expressed at lower levels in tumour tissues compared to tumour-adjacent normal tissue." (PMID 28143425, 2017).
tumor (continued). "Since IGFBP-3 is the main circulating carrier of the IGFs, as well as a regulator of local IGF bioavailability, the absence of IGFBP-3 may affect the access of IGF-1 to cells within the tumor microenvironment." (PMID 27448965, 2016). "I consider combination therapy of first-generation SSAs with cabergoline in symptomatic patients with IGF-1(<1.5-2ULN) while on the maximum tolerated dose of SSA (usually 40 mg octreotide or 120 mg lanerotide monthly) for at least 6 months, regardless of residual tumor size." (PMID 40575269, 2025). "The researchers discovered that tumors from Pik3cap.H1047R tumor-bearing mice treated with a PI3K inhibitor exhibited PANK4 phosphorylation and tumor growth in a PI3K-dependent manner; similar effects were observed in the skeletal muscle of non-tumor-bearing mice and in IGF-1–stimulated cells." (PMID 36329370, 2022). "In contrast, IGF1 expression does not significantly change between the considered conditions, and IGF2 expression tends to decrease in primary tumours compared to normal tissue (p = 0.05) and significantly increases in metastatic samples compared to primary tumours (p = 0.0036)." (PMID 32385236, 2020). "Interestingly, no changes in the phosphorylation of the IGF1-dependent signal transducer AKT (also known as Akt1), as well as of ERK1/2 (Mapk3/Mapk1) and p38 (Ahsa1) were observed in the skeletal muscle of tumor-bearing animals relative to the respective controls." (PMID 31915140, 2020). "However, silencing p62 had a mixed effect on expression of the tumour-promoting factors in quiescent cells, which was quite different from the effects induced by TRB3 depletion; it could not protect them from the IGF-1 induction as did by TRB3 depletion." (PMID 26268733, 2015). "It is likely that a suite of biomarkers, both in the host and tumor will be required rather than single biomarker selection, with some candidates for study in RMS including IGF2, pIGF1R/IGF1R, IGF1, pIRS-1/IRS-1, pIR-A/IR-A, IGFBP-6, and maybe others such as HSPs, PDGFR and Erb2." (PMID 21437217, 2011). "However, we show that: 1) BALF EGF levels are very low and do not differ between naïve and tumor-bearing lungs; 2) macrophages produce trace amounts of EGF in vitro; and 3) EGF does not stimulate neoplastic lung proliferation either alone or in combination with IGF-1 or MØCM (7 and data not shown)." (PMID 21699731, 2011).
cardiovascular disease (159 papers, 2005 to 2025). "Low serum levels of IGF-1 have been associated with an increased risk of chronic degenerative diseases such as type 2 diabetes, cancer, cardiovascular diseases, and neuropathy." (PMID 40863172, 2025). "MiR-1 has been implicated in the development of cardiovascular diseases 36, and its inhibition has been associated with improved cardiac function by enhancing insulin-like growth factor-1 (IGF-1) signaling." (PMID 38994017, 2024). "Few studies have also found an association between high IGF-1 levels and left ventricular hypertrophy in hypertensive patients, a significant predictor of the severity of cardiovascular disease." (PMID 38540997, 2024). "The results of epidemiological studies on the relationship between IGF-1 levels and the risk of cardiovascular disease were inconsistent, as various reports indicated that both an increase and decrease in serum IGF-1 levels were involved in heart disease." (PMID 37372424, 2023). "IGF-1 plays an important role in muscle development and insulin sensitivity, and changes in IGF-1 are correlated with cardiovascular disease risk and mortality." (PMID 34936049, 2022). "Studies on the association of low concentrations of IGF-1 with subclinical cardiovascular disease have yielded contradictory results." (PMID 33989340, 2021). "An imbalance in the GH/IGF1 axis leads to an excessive accumulation of lipids, which increases the risk of cardiovascular disease." (PMID 34220710, 2021). "An association between IGF-1 and cardiovascular diseases has been reported, as well as an inverse association between IGF-1 and lipid profile." (PMID 33101407, 2020). "GH deficiency induces low IGF-1 levels and is associated with cardio-vascular functional and morphological dysfunction, leading a higher mortality risk by cardiovascular disease." (PMID 32655494, 2020). "Abnormalities of GH/IGF-1 axis with GH deficiency, are associated with cardio-vascular functional and morphological dysfunction and leads a higher mortality risk by cardiovascular disease." (PMID 32655494, 2020). "IGF-1 deficiency also increases the risk of cardiovascular disease, and IGF-1 receptor (IGF-1R) activation on heart protects it from effects of myocardial infarction." (PMID 33261185, 2020). "Low intensity exercise has been shown to decrease IGF-1 levels in low-intensity exercisers after a period of six-weeks and is associated with decreased risk of cardiovascular disease." (PMID 27677175, 2016). "In fact, circulating IGF-1 levels are reported to be inversely correlated with the risk of cardiovascular diseases." (PMID 26467524, 2015). "Altered IGF-1 levels have also been implicated in cardiovascular disease, with compelling data suggesting that reduced IGF-1 levels are associated with increased cardiovascular risk." (PMID 24586785, 2014). "Like low IGF-1 levels, ApoE ε4 was previously associated with an increased risk of developing cardiovascular disease and neurodegenerative disease." (PMID 21418511, 2011). "IGF1 levels are associated with an increased risk of cardiovascular disease." (PMID 39965097, 2025). "Studies have shown that low IGF-1 levels may be linked to an increased risk of chronic age-related conditions such as neurodegenerative disorders, Alzheimer’s, diabetes, cardiovascular diseases, and overall decline in strength and immune function." (PMID 38987734, 2024). "Similarly, a meta-analysis conducted in 2015 showed that both low and high IGF-1 levels were associated with an increased risk of cardiovascular disease." (PMID 37372424, 2023). "This may explain the weakened small vessel function associated with low IGF-1 levels in patients with cardiovascular disease (CVD) through LDL cholesterol-activated cytotoxicity and vascular smooth muscle cell apoptosis." (PMID 33905470, 2020).